EPHA3 (EPH receptor A3)
Diseases named in the same sentence as EPHA3 in open-access papers (continued):
Sharing a sentence is not in itself a finding about the gene and the disease.
tumor (continued). "After confirming that the mice had remained tumor-free for 5 weeks, we assessed the functional recall capabilities of the remaining human EphA3 CAR T cells by conducting a contralateral orthotopic rechallenge experiment." (PMID 39111833, 2024). "The tumor volume and weight in the VIM-AS1-overexpressing group were lower than those in the other groups, and EPHA3 overexpression accelerated tumor growth in the VIM-AS1-overexpressing group." (PMID 39617786, 2024). "These tumor cell lines were co‐cultured with FAP‐CAR‐T cells or CAR‐T cells targeting an irrelevant antigen (EphA3) for 48 h, and the level of IL‐2 in the culture supernatant was measured by ELISA." (PMID 38975278, 2024). "Strikingly, complete tumor clearance occurred within 2-3 weeks of implantation in all five mice (100%), mice previously treated with EphA3 CAR T cells." (PMID 39111833, 2024). "EPHA3 was reported related to tumor-specific antigens presented by HLA class II molecules to CD4+T cells." (PMID 38890738, 2024). "For instance, the correlation pattern of these genes with immune infiltration subtypes in KIRP presented a parallel trend, with EphA3 demonstrating elevated expression in C1 and C2, thus implying a tumor-promoting function." (PMID 38952552, 2024). "Subsequently, a range of Eph receptors have been identified as preferentially expressed on tumours, of which EphA2, EphA3, and EphB4 have been a particular focus for therapeutic targeting." (PMID 36830852, 2023). "Accordingly, it has been reported that targeting EphA3 prevents BC growth by disrupting the integrity and function of newly formed tumor stroma and microvasculature." (PMID 37434266, 2023). "This was also evident in mouse xenograft tumours, where EphA3 positive cells were detectable in the stroma and vasculature, while the tumour cell lines themselves lacked EphA3 expression." (PMID 37760615, 2023). "Under laser irradiation, anti-EphA3-TMZ@GNPs enhance tumor cell apoptosis through a chemophotothermal synergistic effect." (PMID 37144620, 2023). "We have identified the cell guidance receptor EphA3 on distinct stromal/fibroblast-like cell types in the tumour microenvironment (TME) that promote growth and angiogenesis, both in human cancers and in mouse tumour models." (PMID 37760615, 2023). "Multiplex immunofluorescence staining also showed EphA3 expression was associated with NG2+ cells, characteristic of perivascular fibroblasts, and this was also reduced in tumours from EphA3 shRNA mice." (PMID 37760615, 2023). "Our results thus indicate an important functional role of EphA3 in mesenchymal CAF-like cells recruited to tumours that promote angiogenesis and tumour growth, and suggest the potential of EphA3 as a therapeutic target in the TME of solid tumours." (PMID 37760615, 2023). "Naked IIIA4 also has antitumour activity in mouse xenografts, in which EphA3 is expressed either in the tumour cells or just in the tumour microenvironment." (PMID 36830852, 2023). "EphA3 is overexpressed in a wide range of tumour types, and we previously found expression particularly in stromal and vascular tissues of the TME." (PMID 37760615, 2023). "In orthotopic mouse GBM xenografts, treatment with radiolabelled EphA3 monoclonal antibody (mAb) IIIA4 blocked tumour growth, supporting the utility of EphA3 as a therapeutic target in GBM." (PMID 36830852, 2023). "EphA3 is a member of the Eph receptor tyrosine kinases that regulate the morphology, adhesion, migration and invasion of cancer cells in vitro as well as tumor growth, invasiveness, angiogenesis and metastasis in vivo." (PMID 37434266, 2023). "In conclusion, we identify the cell guidance receptor EphA3 as a novel marker in distinct myofibroblast-like perivascular/smooth muscle cells in the microenvironment of human tumours and in analogous mesenchymal/fibroblast cells in mouse tumour models." (PMID 37760615, 2023).
tumor (continued). "In an effort to understand the potential contribution of the EphA3 system in the cross-talk among tumor and stromal cells, we performed 3D co-culture motility assays using BC cells and CAFs as model systems." (PMID 37434266, 2023). "Our results therefore indicate an important role of EphA3 in the tumour microenvironment, and suggest the potential therapeutic utility of targeting EphA3-expressing CAFs in solid tumours." (PMID 37760615, 2023). "IHC analysis of tumours showed that those from EphA3 shRNA mice displayed significantly less staining of the endothelial marker CD31, indicative of reduced tumour angiogenesis, with a concomitant decrease in proliferation, as determined by Ki67 staining." (PMID 37760615, 2023). "As a result, anti-EphA3-TMZ@GNPs effectively inhibit T98G glioma tumor proliferation and reverse GBM drug resistance." (PMID 37144620, 2023). "Our results extend these observations, and indicate that EphA3 also has an important role in the TME on mesenchymal progenitor/fibroblast-like cells in tumours, which likely contribute to the perivascular niche and support angiogenesis." (PMID 37760615, 2023). "EphA3 suppression reduced levels of MSCs in tumours, including cells resembling perivascular and myofibroblast-like CAFs, and was associated with decreased blood vessel density and cell proliferation in tumours." (PMID 37760615, 2023). "ATAC-seq reveals that it induces EPHA3, which is a tumor neoantigen and tumor-suppressor gene, thus demonstrating a novel mechanism of action." (PMID 35624662, 2022). "EPHA3 is one of the potential anticancer targets, with up-regulation and tumor-promoting roles in a range of human cancers." (PMID 36505846, 2022). "While tumor stimulatory and inhibitory functions have been ascribed to EPHA3, most evidence suggest that EPHA3 is a tumor suppressor." (PMID 35624662, 2022). "Immunohistochemical staining results were consistent with this finding, as indolium 1-treated tumor tissue samples had more positivity for EPHA3 compared to the controls." (PMID 35624662, 2022). "Conversely, EphA3 suppressed tumors by disrupting the tumor stromal microenvironment in mouse xenografts." (PMID 35551177, 2022). "Patient LGS119 had two detected mutations (EPHA3 and ATRX) in her initial tumor, and these mutations were also detected in tumor samples obtained when the patient had a recurrence 17 months after the initial surgery." (PMID 36528667, 2022). "Prior studies have confirmed that the pro-tumor role of ADAM10 is linked to the interaction among ADAM10, EphA3, and ephrin-A5." (PMID 35551177, 2022). "This suggests that EphA3 has a tumour-suppressive effect on ESCC; however, the specific downstream pathway of Rho GTPase, affected by EphA3, is not well characterised." (PMID 36291586, 2022). "Published research suggested a link between increased EPHA3 expression and tumor depth, stage, and metastasis in gastric cancer." (PMID 35264657, 2022). "This study suggested that EphA2, EphA3, EphA4, and EphA5 can act as tumor-inhibiting factors as well as biomarkers for the prognosis of BC." (PMID 34221956, 2021). "EphA2 and EphA3 are commonly expressed in GBM, including in regions of tumor neovasculature, tumor-associated immune cells, and tumor-infiltrating cells, and associated with poorer outcomes in GBM patients." (PMID 34926242, 2021). "EphA2 expression is highly correlated with the tumor-propagating potential of GBM cells with stem-like properties while elevated levels of EphA3 help to maintain tumorigenicity in tumor-initiating cells." (PMID 33673213, 2021). "To identify a key regulator of tumor growth downstream of IL-26/EphA3 interaction in TNBC, we performed pathway analysis by DNA microarray of HCC70 cells treated with IL-26 and gefitinib." (PMID 34021125, 2021). "This is the first study to demonstrate the feasibility of successfully targeting and imaging EphA3 in the tumor microenvironment, with some early signals of therapeutic effect." (PMID 32397088, 2020).
tumor (continued). "In our study, the combination of two and three proteins (EGFR, HER4 and EphA3) or the combination of these proteins with CA19–9 was an independent prognostic factor for tumor recurrence." (PMID 32093644, 2020). "Biodistribution of the EphA3 antibody IIIA4 was also explored, using 111In- and 125I-labeled antibody, demonstrating clear tumor accumulation in an EphA3-overexpressing xenograft." (PMID 32397088, 2020). "Specifically, EphA2 and EphA3 have been shown to be expressed individually in 60% of GBM patients, including in regions of tumor neovasculature, tumor-associated immune cells, and tumor-infiltrating cells." (PMID 32340173, 2020). "Multivariate cox regression demonstrated that EGFR, HER4, EphA3 or the panel of high expression of these proteins was an independent prognostic factor for tumor recurrence." (PMID 32093644, 2020). "EPHA3 has the ability to function as an indicator in both kinase-dependent and kinase-independent manners, either by promoting or suppressing the tumor." (PMID 31262977, 2019). "The tumor and stroma cells that are dependent on ligand and EPHA3 apoptosis indicated that wild-type EPHA3 was resistant to the tumor in non-small-cell lung carcinoma (NSCLC)." (PMID 31262977, 2019). "Providing further evidence for the potential suitability of monoclonal antibodies targeting EphA3, a bispecific antibody against EphA2/A3 reduced clonogenicity in vitro and decreased tumour burden in vivo." (PMID 31616641, 2019). "The number of Ki67 positive cells was elevated in αDG+/EphA3+/vimentin+ tumour regions compared to other regions, suggesting this tumour compartment was more mitotically active." (PMID 31463571, 2019). "We next performed IHC on sequential GS tumour tissue sections to determine the localisation of αDG, βDG, EphA2 and EphA3." (PMID 31463571, 2019). "Our data demonstrate that EphA3 can be effectively targeted using both ADC or RIT approaches, and that EphA3 mAbs cross the BTB to allow tumour-specific targeting." (PMID 30562956, 2018). "Here, we build upon our existing body of work and the work of others to characterize EphA3 as a tumour-specific therapeutic target for the treatment of GBM." (PMID 30562956, 2018). "To further assess tumour penetration, we engrafted the EphA3-positive primary model WK1 into the striatum of a NOD/SCID mouse." (PMID 30562956, 2018). "Recent findings have proposed that EphA2 and EphA3 not only sustain the survival of GBM primary lines but also promote the renewal of tumor-propagating cells with stem-like characteristics (TPC)." (PMID 29849945, 2018). "EphA3 knockdown (KD) induced tumour cell differentiation, apoptosis, and reduced tumour formation in vivo." (PMID 30562956, 2018). "IIIA4-USAN treatment led to a significant (p < 0.01) reduction in EphA3 mRNA levels in these tumours." (PMID 30562956, 2018). "EphA3 has been shown to be elevated in a number of haematological cancers and solid tumours, with both oncogenic and tumour suppressive functions being described." (PMID 30562956, 2018). "Mice treated with an anti-EphA3 antibody showed a reduction of tumor growth and a destruction of tumor stroma and vasculature." (PMID 28415715, 2017). "Recently, Vail and colleagues reported that microenvironment of different human cancers and mouse tumor xenografts were positive for EphA3 expression." (PMID 28415715, 2017). "Tumor samples showed variable levels of EPHA3 expression that ranged from undetectable to high expression." (PMID 28169277, 2017). "We produced a highly potent eA5-based cytotoxin that kills tumor cells over-expressing receptors EphA3, EphA2, and also EphB2." (PMID 27494882, 2016). "EphA3 depletion or treatment with specific anti-EphA3 monoclonal antibody reduced cell tumorigenicity in vivo by targeting tumor-initiating cells." (PMID 27494882, 2016). "EphA3 was detected in the perivascular space, but it showed a limited co-staining with EphA2 within the tumor area." (PMID 27494882, 2016).
tumor (continued). "EphA3 is thus present on tumor cells, tumor-initiating cells, infiltrating tumor cells, and tumor-infiltrating cells of monocytic origin." (PMID 27494882, 2016). "Both approaches clearly indicated that EPHA3 improves chemosensitivity and suppresses tumor growth in vivo, which manifests that EPHA3 acts as a tumor suppressor in SCLC." (PMID 27101199, 2016). "To better understand the biological function of EPHA3 in SCLC, we investigated its potential role in tumor growth and chemoresistance through loss- and gain-of-function approaches in human SCLC cell lines (H69, H69AR, H446, H146, and H1688)." (PMID 27101199, 2016). "The role of EphA3 is to maintain the de-differentiated state of tumor cells in the more aggressive mesenchymal subtype." (PMID 27494882, 2016). "Taken together, these results suggested a possible role of EphA3 in tumor-infiltrating macrophages/leukocytes." (PMID 27494882, 2016). "EphA2 was previously found in infiltrative and tumor-initiating cells and EphA3 is also overexpressed in the invading ring of the tumor." (PMID 27494882, 2016). "The novel eA5-based cytotoxin was neutral to normal cells tested, but effectively killed tumor cells demonstrating overexpression of EphA3, EphA2, and EphB2 receptors." (PMID 27494882, 2016). "Overall, our findings are consistent with the results from NSCLC and confirm that EPHA3 is involved in regulating the chemoresistance of SCLC with tumor-suppressing effects." (PMID 27101199, 2016). "EphA3 co-localized with macrophage/leukocyte markers, suggesting EphA3 expression on tumor-infiltrating cells of bone marrow origin." (PMID 27494882, 2016). "Surprisingly, all three monocyte/macrophage markers co-stained with EphA3 in a sub-population of cells surrounding tumor vasculature and in the core of the tumor." (PMID 27494882, 2016). "Along this line, it was shown that co-expressed in the same tumor cell Ephrin A3 binding in cis (ligand and receptor on the same cell) can block EphA2 and EphA3 in trans (ligand and receptor on different cells) ligand binding." (PMID 27533087, 2016). "EphA3 was localized in scattered areas of the tumor, the invasive ring, and niches near tumor vessels." (PMID 27494882, 2016). "With respect to its putative role in tumorigenesis, previous studies have indicated that EPHA3 can signal both in a kinase-dependent and kinase-independent manner, inducing both tumor-promoting and tumor-suppressing effects." (PMID 25713296, 2015). "EphA3 has important roles in growth and migration/invasion of some cancer cells in vitro as well as a role in tumor growth, invasiveness, angiogenesis, and metastasis in vivo." (PMID 25978371, 2015). "In our previous work, 1504-siRNA silencing of EphA3 was potent tumor suppressor via the classic tumorgenesis pathway (AKT signaling pathway)." (PMID 25978371, 2015). "Two human tumor cell lines highly expressing EphA3 and TERT(C4-2B and HGC27 cell) and cell line that expressed little EphA3 and TERT (2BS cell) were infected with Ad-TERTp-E1A-1504, Ad-TERTp-E1A-NC, or Ad-ΔE1A-1504 or Ad-ΔE1A-NC at the indicated titers." (PMID 25978371, 2015). "In many studies, soluble EphA3 (Fc fusion proteins) and anti-Eph Mabs, agonists and drugs that stimulate Eph receptor degradation were utilized as anti-tumor drugs." (PMID 25978371, 2015). "Filtering yielded 46 likely somatic mutations in the tumor, of which 7 (affecting EIF4A1, EPHA3, FAF1, IPO8, KIAA1377, LIMCH1, and NIPBL) were confirmed in the RNASeq results." (PMID 25861239, 2015). "In summary, Ad-TERTp-E1A-1504 did not harm TERT-negative cells but was oncolytic and inhibited TERT- and EphA3-positive tumor cells, which was also validated in vivo." (PMID 25978371, 2015). "Strongly EPHA3-immunoreactive stellate-like cells are found scattered within normal BM and, with increased density, in the tumor stroma of bone metastases." (PMID 25485970, 2014). "Our classification is in accordance with prior knowledge about the tumor suppressor activity of EPHA3." (PMID 21575214, 2011).
tumor (continued). "The consensus of the classifiers identifies DCLK3, MMP2, TGM3 as oncogenes and PIK3C3 and EPHA3 as tumor suppressors." (PMID 21575214, 2011). "Blocking EphA receptor signaling using soluble EphA2-Fc and EphA3-Fc receptors decreased tumor vascular density, tumor volume and cell proliferation in vivo, suggesting that the soluble receptors inhibited blood vessel recruitment by the tumor." (PMID 20224755, 2010). "EphA3 expression is elevated in primary medulloblastomas compared to normal cerebellum, with the highest levels observed in the Uw-402 cell line and normal fetal brain, suggesting its involvement in both neural development and tumor biology." (PMID 41200151, 2025). "Notably, mice rechallenged with tumors on the contralateral side remained tumor-free for over 6 months, underscoring the therapeutic potential of EphA3-directed immunotherapy." (PMID 41200151, 2025). "Antibody targeting or knock-down of TME-expressed EphA3 decreased angiogenesis and tumour growth." (PMID 39780187, 2025). "In addition, EphA3 is expressed on distinct stromal/fibroblast-like cell types in the tumor microenvironment (TME) that promote growth and angiogenesis and genetic knockdown of EphA3 reduces angiogenic capacity." (PMID 39111833, 2024). "In summary, while EphA2 promotes cancer progression in ESCC, EphA7, EphA3, and EphA5 act as tumor suppressors, suggesting that members of the Eph family may have opposing effects depending on the tumor context." (PMID 39839790, 2024). "Moreover, EphA3 exhibited correlations with the immune score, a metric assessing the presence of infiltrating immune cells (P = 0.0011) and tumor purity (Estimate score) (P < 0.0001)." (PMID 38952552, 2024). "EphA3 expression is seen to be related to tumor progression by angiogenic activity in GC." (PMID 39839790, 2024). "In summary, most Eph receptors (EphA1, EphA2, EphA3, EphA4, EphA5, and EphA7) function as promoters of GC progression, influencing metastasis, tumor invasion, angiogenesis, and drug resistance, while EphA1 has a more complex role depending on tumor differentiation." (PMID 39839790, 2024). "In this case, the evaluation covered temozolomide-conjugated gold nanoparticles functionalized with an antibody against the EPHA3 (anti-EPHA3-TMZ@GNP) via intranasal administration bypassing the blood–brain barrier (BBB) in a Sprague Dawley rat orthotopic GBM tumour model." (PMID 38247816, 2024). "Despite its oncogenic roles in gastric carcinoma and glioblastoma multiforme, EphA3 may function as a tumor-suppressor in lung adenocarcinomas through suppressing ATK activation." (PMID 38811954, 2024). "Inhibition of EPHA3 activity could potentially impede tumor metastasis by preventing cytoskeleton reorganization and cell retraction mediated by its downstream signaling pathways." (PMID 38233802, 2024). "Interestingly, EphA3 was expressed in myofibroblasts and other immune-modulatory CAF subtypes, consistent with the altered T cell infiltrate in tumours in our mice following EphA3 knockdown." (PMID 37760615, 2023). "Our novel transgenic mice, with specific knockdown of EphA3 expression in the TME of implanted syngeneic tumours, showed reduced tumour growth and angiogenesis, and associated defects in stem-like and angiogenic properties in mesenchymal stromal progenitor cells." (PMID 37760615, 2023). "Knockdown of EphA3 expression in the TME in syngeneic mouse tumours reduced mesenchymal stromal/fibroblast-like cells in tumours, with corresponding reductions in tumour vasculature and tumour growth, and increased immune infiltrate, indicating an important role in tumour progression." (PMID 37760615, 2023). "Eph receptors have also been identified in many tumor infiltrating cells; for example, EphA3 is extensively expressed in stromal fibroblasts in many solid tumors, which may promote tumor progression and invasiveness, and also inhibit the anti-cancer immunity." (PMID 37637034, 2023).